FANCI (FA complementation group I)
Diseases named in the same sentence as FANCI in open-access papers (continued):
Sharing a sentence is not in itself a finding about the gene and the disease.
cancer (48 papers, 2013 to 2025). A tumor composed of atypical neoplastic, often pleomorphic cells that invade other tissues. "Further Cox regression and Kaplan–Meier survival analyses demonstrate that high FANCI expression is significantly associated with poor prognosis in cancers such as KIRP, LIHC, PAAD, and ACC." (PMID 40417238, 2025). "Elevated FANCI expression is associated with unfavorable prognoses in cancers such as adrenocortical carcinoma (ACC) and liver hepatocellular carcinoma (LIHC)." (PMID 40417238, 2025). "This study reveals the diagnostic and prognostic value of FANCI across multiple cancers, particularly demonstrating exceptionally high diagnostic accuracy (AUC >0.9) in LIHC and PAAD." (PMID 40417238, 2025). "Dysregulation of the FA pathway, including mutations or altered expression of FANCI, has been linked to genomic instability and increased cancer susceptibility." (PMID 40417238, 2025). "The findings reveal that FANCI is significantly upregulated in most cancer types and closely associated with poor outcomes, suggesting that it plays a key oncogenic role in tumor initiation and progression." (PMID 40417238, 2025). "The CancerSEA database was also utilized for single-cell level investigation of FANCI’s association with the functional states of cancer." (PMID 40417238, 2025). "The research emphasizes the ubiquitous upregulation of FANCI and its importance as both an adverse prognostic marker and a potential diagnostic biomarker in various cancers." (PMID 40417238, 2025). "Collectively, these findings suggest that FANCI expression is intricately linked to cancer progression and severity." (PMID 40417238, 2025). "These chemicals present opportunities for future investigation for the treatment of cancer cases with FANCI variants." (PMID 36833203, 2023). "We also investigate FANCI variant carriers in the context of other cancer types by taking advantage of The Cancer Genome Atlas (TCGA) molecular genetic data sets." (PMID 36833203, 2023). "FANCI, reported as potential with carcinogenesis, is associated with DNA damage repair pathway and cancer sensitization with chemo‐ or radiotherapy." (PMID 37168687, 2023). "The clinical utility of FANCI for diagnosis and management cannot be determined until penetrance for cancer risk is established." (PMID 36833203, 2023). "The identification of germline FANCI c.1813C>T carriers and various somatic FANCI variants across cancer types suggests a possible involvement of FANCI in other cancers and an avenue for future research." (PMID 36833203, 2023). "In cellulo and in vitro analysis of a missense variant found to recur in cancer cases implicates FANCI as a new candidate OC-predisposing gene." (PMID 34861889, 2021). "This was further strengthened by numerous FANCI variations directly associated with many human cancers." (PMID 34884777, 2021). "There have been independent reports of BC cases carrying other FANCI variants with VAF 10−3 to 10−6 in cancer-free individuals." (PMID 34861889, 2021). "Meantime, FANCI mutation is also related to malformations in heart, kidney and limbs, predisposition to cancer development and pigmentary changes in the skin." (PMID 32271791, 2020). "Notably, among the cancers where high FANCI expression is linked to decreased overall survival, LIHC (AUC = 0.909) and PAAD (AUC = 0.978) exhibit significant diagnostic value." (PMID 40417238, 2025). "Notably, in cancers where high FANCI expression is linked to poor prognosis, pathways related to cell cycle checkpoints, DNA replication, and antigen processing and presentation are significantly enriched." (PMID 40417238, 2025). "These charts reveal significant differences in FANCI expression among different molecular subtypes, suggesting that FANCI expression may be associated with specific molecular characteristics of these cancers." (PMID 40417238, 2025).
cancer (continued). "In addition, we examined the methylation patterns of FANCI in cancer, as aberrant DNA methylation is associated with gene dysregulation in oncogenesis." (PMID 40417238, 2025). "Moreover, FANCI expression was found to be connected to immune cell infiltration and tumor mutation burden in select cancers." (PMID 40417238, 2025). "It is unknown if FANCI c.1813C>T contributes to the risk of these cancers, as the variant is more common in the general population compared to other high-risk CPGs (0.6% vs. 0.0001%)." (PMID 36833203, 2023). "As FANCI plays a role in FA-HR pathway it may be associated with phenotypically similar cancer families that have implicated BRCA1 and BRCA2." (PMID 34861889, 2021). "Because the unique nuclear protein complex that ubiquitinates FANCD2 and FANCI leads to formation of DNA repair structures, it is postulated that they may affect cancer risk in a specific manner." (PMID 34549727, 2021). "With these promising results in hand, we assessed FANCI c.1813C>T carrier frequency in available PBL DNA from index OC or BC cases of FC ancestry to determine if this variant plays a role in conferring risk in phenotypically defined cancer families." (PMID 34861889, 2021). "To evaluate the potential pathogenicity of FANCI c.1813C>T; p.L605F, we applied a strategy that took advantage of the observed genetic drift in the FC population by investigating its allele frequency in FC OC and cancer-free subjects." (PMID 34861889, 2021). "Additionally, TCGA cancer cases were identified with somatic variants in FANCI across cancer types." (PMID 36833203, 2023). "Finally, heterozygous deleterious germline mutation BLM and FANCI were identified which could predispose the patient to higher cancer risk." (PMID 35860547, 2022). "Similarly, the effect of risk modifiers in the CARTaGENE cancer-free controls in the context of FANCI variant carriers is unknown." (PMID 34861889, 2021). "Our data suggest that pathogenic FANCI variants may modify OC risk in cancer families." (PMID 34861889, 2021). "Subsequently, we explored the correlation between FANCI expression and tumor mutation burden (TMB) in pan-cancer tissues." (PMID 40417238, 2025). "Subsequent investigations should concentrate on elucidating the mechanistic functions of FANCI in cancer development and assessing its viability as a therapeutic target." (PMID 40417238, 2025). "These hub genes are all significantly interconnected in cancers where FANCI expression influences prognosis (all p < 0.05).The heatmap shows that, compared to normal tissue, most of the top 10 hub genes have higher expression levels in tumor tissue." (PMID 40417238, 2025). "The bar chart showed a significant positive correlation in several cancers, such as KICH, ACC, and PRAD, where higher FANCI expression was associated with increased TMB." (PMID 40417238, 2025). "We investigated the functional role of FANCI across various cancer types using CancerSEA, which allows for the analysis of FANCI’s correlation with multiple functional states of cancer cells at the single-cell level." (PMID 40417238, 2025). "By integrating data from the TCGA and GTEx databases, we systematically analyzed the expression pattern and clinical relevance of FANCI in 33 cancer types." (PMID 40417238, 2025). "In our study, we employed the cBioPortal tool to investigate the pan-cancer genetic alterations of the FANCI gene." (PMID 40417238, 2025). "In summary, this study aims to provide a comprehensive understanding of FANCI’s role in cancer, highlighting its potential as a biomarker for prognosis and diagnosis, and uncovering novel therapeutic targets." (PMID 40417238, 2025). "These survival curves suggest that high FANCI expression is significantly correlated with reduced overall survival in these cancer types." (PMID 40417238, 2025).
cancer (continued). "Overall, these GSEA results indicate that FANCI plays a significant role in several key pathways across different cancers, particularly those related to cell cycle regulation, immune response, and DNA replication." (PMID 40417238, 2025). "This study aims to investigate FANCI expression across multiple cancer types using data from The Cancer Genome Atlas (TCGA) and Genotype-Tissue Expression (GTEx) databases." (PMID 40417238, 2025). "Within pan-cancer tissues, the expression of FANCI exhibited a positive correlation with the majority of m1A, m5C, and m6A methylation modifications, underscoring FANCI’s potential role within the intricate regulatory network of mRNA modifications." (PMID 40417238, 2025). "By integrating multi-omics data and employing robust bioinformatics analyses, we hope to elucidate the complex interactions and regulatory mechanisms involving FANCI in different cancer contexts." (PMID 40417238, 2025). "Given the diverse roles of FANCI across different cancers, a comprehensive pan-cancer analysis is warranted to elucidate its expression patterns, prognostic significance, and potential as a diagnostic biomarker." (PMID 40417238, 2025). "In summary, this study, through an integration of multi-omics analyses and preliminary experimental validation, systematically delineates the expression patterns, clinical significance, and potential functions of FANCI across cancers." (PMID 40417238, 2025). "Drawing from the forest plot and the Cox proportional hazards model analysis, this study elucidates the relationship between FANCI expression and overall survival across various cancer types." (PMID 40417238, 2025). "In summary, FANCI presents as a promising biomarker for cancer prognosis and diagnosis, with potential implications for therapeutic interventions." (PMID 40417238, 2025). "The CPTAC dataset provides insights into FANCI protein expression across various cancer types, with box plots illustrating significantly elevated levels in COAD, PAAD, LIHC, LUAD, OV, HNSC, and UCEC relative to normal tissues." (PMID 40417238, 2025). "Each of these studies has demonstrated an important clinical role for the FANCI protein in various cancers." (PMID 39767562, 2024). "The genes FAN1, MSH6, and FANCI were among those with the highest number of VUS, complicating clinical decision-making due to the uncertain impact of these variants on hereditary cancer risk." (PMID 39710803, 2024). "The same study also showed that FANCI inactivation can transform cancer cells from a resistant state to one that can be eliminated with DNA-damaging chemotherapy." (PMID 39767562, 2024). "There are 12 cancer-related drugs that interact with FANCI, 7 of which are chemotherapies and 5 of which are targeted therapies." (PMID 36833203, 2023). "The moderately increased carrier frequency of FANCI c.1813C>T in TCGA cancer cases (1.6%) compared to gnomAD cancer-free controls (1.3%) is intriguing, suggesting a role for this variant in risk (p = 0.007)." (PMID 36833203, 2023). "In the pan-cancer forest plot, the ACC patients with upregulated FANCI showed an extremely high risk of death (HR = 11.8983)." (PMID 37324186, 2023). "Collectively, these findings expand on the characteristics described for OC cases carrying FANCI c.1813C>T; p.L605F and suggest the possible involvement of FANCI in other cancer types at the germline and/or somatic level." (PMID 36833203, 2023). "Seeing as FANCI has a similar function to FANCD2 in the DDR pathway and is closely related, it is necessary to investigate the role of FANCI in cancer." (PMID 37324186, 2023). "We examined the connection between FANCI expression and the prognosis in 33 diverse cancers using the GEPIA database to explore the prognostic value of FANCI in different cancers." (PMID 38077326, 2023).
cancer (continued). "We previously reported carriers of FANCI c.1813C>T and other potentially pathogenic FANCI variants in BC cases, a disease associated with OC risk genes, and a review of the literature also indicated that there were FANCI carriers in other cancer types." (PMID 36833203, 2023). "To further investigate the role of FANCI in other cancer types we investigated the germline carrier frequency of FANCI c.1813C>T in 10,389 cancer cases from the TCGA PanCancer data set." (PMID 36833203, 2023). "LIHC patients with high FANCI levels (FANCIhigh) suffered faster cancer recurrence than LIHC patients with low FANCI levels (FANCIlow)." (PMID 37324186, 2023). "Heterozygous carriers of FANCI c.1813C>T were identified more commonly in OC families negative for BRCA1 and BRCA2 pathogenic variants compared to FC cancer-free controls." (PMID 36833203, 2023). "FANCI c.1813C>T cancer-free control carriers were more likely to have a first-degree relative with OC, suggesting a role in the risk of OC." (PMID 36833203, 2023). "Therefore, suggesting that FANCI is mutated in cancers, and may play a vital role." (PMID 36428813, 2022). "Though the confidence interval is wide, due to the small sample size, our findings are supported by the observation that cancer-free FANCI c.1813C>T carriers (female/male) were more likely to have a first-degree relative with OC in the FC population." (PMID 34861889, 2021). "Combined, these suggest that FANCD2 and FANCI regulate the further molecular machineries for chromatin-based processes and many others, preventing the human genome from going awry for cancer and other human diseases." (PMID 34884777, 2021). "Amplifications of 8 FA genes are identified across 22 carcinomas; 2 of the carcinomas contain amplification in two FA genes (FANCG with FANCI and BRIP1 with RAD51C)." (PMID 26438152, 2015). "This indicates that FANCI may play a role in regulating the tumor immune microenvironment and could serve as a potential biomarker for immune-related cancer characteristics." (PMID 40417238, 2025). "Previous studies have highlighted the involvement of FANCI in various cancer types." (PMID 40417238, 2025). "Additionally, we will utilize the CancerSEA database to study FANCI’s correlation with cancer functional states at the single-cell level." (PMID 40417238, 2025). "In various cancers, FANCI was positively correlated with T helper cells, Tcm, and Th2 cells." (PMID 40417238, 2025). "A spectrum of somatic variants in FANCI has also been identified in various cancer types that were not restricted to any specific gene region." (PMID 39767562, 2024). "This extends the evidence that inactivation of FANCI may convert cancer cells from a resistant state to an eradicable state under the stress of DNA-damaging chemotherapy." (PMID 38023254, 2023). "Significant levels of FANCI expression were present in almost all cancers." (PMID 37324186, 2023). "Interestingly, the overall carrier frequency of FANCI c.1813C>T at 1.6% (171/10,389) was significantly higher in the TCGA PanCancer cases than in non-cancer individuals in gnomAD (1.3%, 1787/134,164; Pearson’s χ2 = 7.3, p = 0.007)." (PMID 36833203, 2023). "Akt is a critical mediator in cancer, and FANCI negatively regulates AKT activation." (PMID 38077326, 2023). "With the progression of LIHC, the expression of FANCI is upregulated, which may indicate that FANCI contributes to cancer progression." (PMID 37324186, 2023). "Based on known cancer predisposing genes curated from COSMIC database and other pan-cancer germline genomic studies, we found a total of 6 damaging or potentially damaging heterozygous germline variants including missense mutation of BLM and FANCI." (PMID 35860547, 2022). "Lastly, we investigated Canadian non-FC (CDN) and Australian (AUS) cancer cases for rare candidate FANCI variants." (PMID 34861889, 2021). "As FANCI-associated FA cases are rare, the incidence of cancer in biallelic carriers has not been reported." (PMID 34861889, 2021).
cancer (continued). "Given the unique genetic architecture of the FC population of Quebec, it is likely that carriers of FANCI c.1813C>T have common ancestors as has been shown with carriers of frequently occurring pathogenic variants in BRCA1, BRCA2, and MSH6 in cancer families." (PMID 34861889, 2021). "Why are the roles of FANCD2 and FANCI in cancer predisposition not identified, though they are central participants in the FA pathway?" (PMID 32300589, 2020). "We found monoallelic functionally deleterious mutations in three genes of the FA family, namely RAD51C (FANCO), FANCD2 and FANCI genes, the latter two not previously associated with cancer risk." (PMID 29659569, 2018). "This suggests that FANCI expression may be related to genomic instability in these cancers." (PMID 40417238, 2025). "Our results indicate that FANCI is significantly overexpressed in most cancer types, implying that by enhancing DNA damage repair capabilities, it may help cancer cells adapt to high levels of DNA damage stress, thereby promoting oncogenesis and tumor progression." (PMID 40417238, 2025). "Furthermore, genes with R-loop changes were significantly enriched in cancer progression–associated pathways, such as Ras and MAPK signaling pathways; thus, FANCI may be involved in LUAD progression by regulating the R-loops." (PMID 38200551, 2024). "Additionally, inhibition of FANCI could sensitize cancer cells to crosslinking agents, which would reduce the dosage and side effects of crosslinking agents." (PMID 37324186, 2023). "Overall, these results emphasize the significant correlation of FANCI expression with immune infiltration, TMB, immune subtypes, and molecular subtypes in various cancers." (PMID 40417238, 2025). "The deubiquitinating enzyme USP1:UAF1, a therapeutic target in cancer, normally removes ubiquitin from FANCD2 unless FANCI is also modified." (PMID 40447800, 2025). "Germline FANCI c.1813C>T was initially identified in HGSC cases, but as shown in our study, it can be observed across many cancer types in the TGCA PanCancer Atlas." (PMID 36833203, 2023). "Other high-penetrant cancer genes BRCA1, APC, STK11 and moderate-penetrant genes BRIP1, CDKN2A, FANCI and MET had a similar frequency 1 (5.8%)." (PMID 37277882, 2023). "Consistent with the results from the cancer cell lines, targeting BRIP1 as well as several other components of the FA pathway, such as FANCD2 and FANCI, significantly impaired the fitness of ALDH2 KO cells as compared to the WT." (PMID 34454516, 2021). "Our results reveal how monoubiquitinated FANCI:FANCD2, defective in many cancer types and all cases of FA, is activated upon DNA binding." (PMID 32167469, 2020). "The signatures identified in tumours from FANCI c.1813C>T carriers were compared to those exhibited by HGSC tumours, as there have been no reports attributing mutational signatures to cancers harbouring deleterious FANCI variants." (PMID 36833203, 2023). "Similarly, anti-FANCI inhibitors have the potential to overcome chemoresistance in LIHC, and combined with crosslinking agents have the potential to kill chemoresistant cancer cells." (PMID 37324186, 2023). "Moreover, pan-cancer patients with upregulated PLK1, CEP55, FANCI, NEK2, and PTTG1 exhibited a poorer overall survival rate and disease-free survival." (PMID 37274251, 2023). "Here, we aimed to investigate the molecular genetic characteristics of FANCI, as they have not been described in the context of cancer." (PMID 36833203, 2023). "Of these, seven genes (BRIP1, ERCC4, FANCD2, FANCG, FANCI, MAD2L2, PPP2R2A) were previously related to the platinum sensitivity/resistance of different types of cancer cells, with NPEPPS being reported for the first time as a platinum drug sensitivity regulator." (PMID 35209078, 2022).